SHMT2 (serine hydroxymethyltransferase 2)
Diseases named in the same sentence as SHMT2 in open-access papers (continued):
Sharing a sentence is not in itself a finding about the gene and the disease.
neuroblastoma (14 papers, 2016 to 2025). Neuroblastoma (NB) is the most common solid, extracranial childhood tumor. "In MYC-amplified neuroblastoma, hypoxic stress induces the expression of SHMT2, and knock-down of SHMT2 reduces tumorigenesis." (PMID 38331894, 2024). "SHMT2 expression is increased under hypoxic conditions in human neuroblastoma cells SHMT2 under hypoxic conditions increases the generation of NADPH and glutathione (GSH), and GSH maintains the cell’s redox status removing reactive oxygen species (ROS)." (PMID 39189649, 2024). "In MYC-amplified neuroblastomas, the correlation between SHMT2 and HIF1α was associated with poor patient prognosis, confirming the essential role of HIF1-induced SHMT2 regulation in maintaining therapy-resistant hypoxic cell survival." (PMID 33801846, 2021). "Knockdown of SHMT2 reduced 13C-glycine level in hypoxic neuroblastoma cells labelled with 13C-serine, consolidating the function of SHMT2 in converting serine to glycine." (PMID 34359884, 2021). "In neuroblastoma patient samples, there was a significant correlation between SHMT2 and hypoxia-inducible factor-1 α (HIF-1α), and SHMT2 expression correlated with worse patient prognosis." (PMID 33066813, 2020). "This study detected a correlation between high expression of SHMT2 and poor prognosis in neuroblastoma patients." (PMID 29312889, 2017). "Expression of SHMT2 in neuroblastoma cells seems to be controlled by the collaborative action of c-Myc and HIF1α." (PMID 29312889, 2017). "SHMT2 was also induced by HIF-1 under hypoxia in neuroblastoma cells." (PMID 34359884, 2021). "MYCN can also drive transcription of ATF4 in neuroblastoma cells, and it was demostrated that targeting either MYCN or ATF4 leads to decreased expression levels of PHGDH, PSAT1, SHMT2, MTHFD2, and MTHFD1L." (PMID 37949226, 2023). "IHC study revealed a positive correlation between SHMT2 and HIF-1α protein expression in human neuroblastoma tissues." (PMID 34359884, 2021). "In addition, recent studies revealed a role of IGF2BP1 in promoting neuroblastoma metastasis via extracellular vesicles guiding SEMA3A and SHMT2 expression." (PMID 37246217, 2023). "Studies have shown that SHMT2 can be co-induced by HIF1αand Myc in neuroblastoma tumors, and, in the absence of oxygen, SHMT2 maintains cell growth by balancing the NADPH/NADP+ratios." (PMID 37108312, 2023). "Besides, it was reported that the first mitochondrial enzyme of the folate cycle, termed serine hydroxymethyl transferase 2 (SHMT2) is essential for maintaining mitochondrial NADPH and GSH level during hypoxia in neuroblastoma cell lines." (PMID 29312889, 2017). "Co-induction of SHMT2 by HIF1α and Myc maintains cell growth by balancing the NADPH/NADP+ ratios in neuroblastoma tumors upon lack of oxygen." (PMID 40097394, 2025).
gastric cancer (13 papers, 2021 to 2025). A primary or metastatic malignant neoplasm involving the stomach. "The development of gastric cancer is associated with the upregulation of SHMT2 mediated by miR-449a, while circ_0063526 enhances drug resistance in gastric cancer through modulation of the miR-449a/SHMT2 axis." (PMID 40427537, 2025). "Weida Wang reported that SHMT2 levels are increased in gastric cancer tissues and increase the stability of hypoxia-inducible factor 1α (HIF1α)." (PMID 39309860, 2024). "In gastric cancer cells, SHMT2 modulates the stability of HIF1α, thus controlling a network of hypoxia-responsive genes that have regulatory effects on complementary pathways, including VEGF and STAT3." (PMID 39309860, 2024). "The researchers also found that after the silencing of USP32 expression in gastric cancer, the expression of SHMT2 decreased." (PMID 37679322, 2023). "Clinically, SHMT2 was overexpressed in gastric cancer, oesophageal cancer and colorectal cancer (CRC) tissues at both the mRNA and protein levels, as measured by qRT-PCR and immunohistochemistry assays, compared to paired normal adjacent tissues." (PMID 34476002, 2021). "However, the precise role and function of SHMT2 in gastric cancer (GC) remain poorly understood." (PMID 37108312, 2023). "Another study found that early and late stages of gastric cancer had higher expression levels of the USP32 and SHMT2 proteins, and immunohistochemistry analysis supported these findings." (PMID 37679322, 2023). "Beyond these examples, SIRT5 has also been found to inhibit gastric cancer invasion by catalyzing the desuccinylation of S100A10 protein, and it can desuccinylate the K280 site of serine hydroxymethyltransferase 2 (SHMT2) protein, thereby inhibiting osteosarcoma development." (PMID 39944690, 2025). "Furthermore, SHMT2 regulates HIF1α expression through both enzymatic and non-enzymatic functions in gastric cancer." (PMID 40097394, 2025).
lymphoma (10 papers, 2022 to 2024). A malignant (clonal) proliferation of B- lymphocytes or T- lymphocytes which involves the lymph nodes, bone marrow and/or extranodal sites. "For example, SHMT2 induces changes in DNA and histone methylation patterns leading to promoter silencing of tumor suppressor genes in lymphoma." (PMID 38272883, 2024). "For example, inhibition of SHMT2 in lymphomas induces alterations in DNA and histone methylation, which promotes lymphatic injury." (PMID 38625586, 2024). "The finding that the Serine Hydroxymethyltransferase 2 (SHMT2) is an oncogenic driver of BCL2-expressing lymphomas further underscores the crucial role of serine one-carbon metabolism in B cell pathology." (PMID 35580618, 2022). "For example, SHMT2 knockdown disrupted the TCF3 transcriptional survival program in lymphoma." (PMID 36213384, 2022). "In addition, another study described that SHMT2 and BCL2 cooperated to promote the occurrence of lymphoma through the silencing of epigenetic inhibitors, as the enhancement of SHMT2 metabolic enzyme activity was sufficient to convert normal B cells into B-cell lymphoma." (PMID 36110969, 2022).
lung adenocarcinoma (9 papers, 2020 to 2025). A carcinoma that arises from the lung and is characterized by the presence of malignant glandular epithelial cells. "Previously, SHMT2 expression has been shown to be inversely associated with tumor-infiltrating lymphocytes in the tumor microenvironment of patients with lung adenocarcinoma, using TIMER and TISIDB online databases." (PMID 38160212, 2024). "We demonstrated for the first time that MAPK1 regulates serine catabolism through phosphorylating SHMT2 in lung adenocarcinoma." (PMID 38460155, 2024). "An interesting question that needs to be further answered is why SHMT2‐Ser90 phosphorylation affects only the m6A methylation of total RNA and how this selectivity is achieved in lung adenocarcinoma." (PMID 38460155, 2024). "We measured the protein expression of SHMT1 and SHMT2 in lung adenocarcinoma cells and human bronchial epithelial cells (BEAS‐2B)." (PMID 38460155, 2024). "Immunohistochemical analysis was performed to confirm SHMT2 expression in lung adenocarcinoma and adjacent normal lung tissues." (PMID 38577602, 2024). "In this study, we found that the proliferation of lung adenocarcinoma cells was more strongly dependent on SHMT2 than on SHMT1." (PMID 38460155, 2024). "SHMT2 knockdown inhibited the proliferation, migration, and epithelial-mesenchymal transition of lung adenocarcinoma A549 and H1299 cells." (PMID 38577602, 2024). "We further measured the expression of SHMT2 in a lung adenocarcinoma tissue microarray." (PMID 38460155, 2024). "Thus, this study reveals a new regulatory mechanism for SHMT2 regulation in lung adenocarcinoma and lays a theoretical basis for targeting SHMT2 as a therapeutic target in lung adenocarcinoma." (PMID 38460155, 2024). "However, the prognostic role of SHMT2 in lung adenocarcinoma (LUAD) and its relationship with immune cell infiltration is not clear." (PMID 33928169, 2021). "We clarified that the inhibitory effect of SHIN1 on lung adenocarcinoma cells was mediated mainly by SHMT2 but not by SHMT1." (PMID 38460155, 2024). "However, expression and role of SHMT2 in lung adenocarcinoma (LUAD) had not been fully investigated." (PMID 40432803, 2025). "Here we analyzed expression of SHMT2, and 12 additional enzymes involved in serine/glycine/1-carbon metabolism in a NSCLC primary tumor, a cognate PDX model, cell line LPC43 that was derived from the PDX, and the established lung-adenocarcinoma-derived cell line HCC827." (PMID 32903271, 2020).
oral squamous cell carcinoma (8 papers, 2020 to 2024). "SHMT2 expression was positively correlated with advanced pathological grading of oral squamous cell carcinoma." (PMID 38625586, 2024). "SHMT2 expression was firstly analyzed among 343 samples from the TCGA database, we found that SHMT2 was significantly up-regulated in 313 oral squamous cell carcinoma (OSCC) samples, when compared with 30 normal tissue samples (P < 0.0001)." (PMID 33863325, 2021). "This study focused on the expression of mitochondrial serine hydroxymethyltransferase (SHMT2) in oral squamous cell carcinoma (OSCC) and its correlation with clinical traits and the prognosis of OSCC patients." (PMID 33163414, 2020).
esophageal cancer (7 papers, 2021 to 2025). A primary or metastatic malignant neoplasm involving the esophagus. "Under hypoxic conditions, the upregulated expression of serine hydroxymethyltransferase 2 (SHMT2) enhances the glycolytic activity of esophageal cancer (EC) cells." (PMID 40584966, 2025). "Hypoxia stabilizes SHMT2 lactation, thereby promoting glycolysis and stemness of esophageal cancer cells." (PMID 40097394, 2025). "Serine hydroxymethyl transferase 2 (SHMT2) is involved in esophageal cancer progression by interacting with Methylenetetrahy-drofolate Dehydrogenase 1 Like (MTHFD1L), while hypoxia-induced SHMT2 Kla in turn enhanced MTHFD1L expression and accelerated the malignant progression of EC cells." (PMID 40563450, 2025). "In esophageal cancer, hypoxia stabilizes serine hydroxymethyltransferase 2 (SHMT2) via lactylation, which enhances its interaction with the key enzyme in one-carbon metabolism, methylenetetrahydrofolate dehydrogenase (NADP+ dependent) 1-like (MTHFD1L), thereby facilitating a malignant phenotype 57." (PMID 40128358, 2025). "However, there are few studies of SHMT2 in esophageal cancer (EC), and the related functions and mechanisms also need to be further explored." (PMID 37932821, 2023). "In addition, SHMT2 was also upregulated in esophageal cancers, but there was no statistical significance." (PMID 34149818, 2021).
intrahepatic cholangiocarcinoma (7 papers, 2018 to 2025). A carcinoma that arises from the intrahepatic bile duct epithelium in any site of the intrahepatic biliary tree. "The objective of the present study is to explore the expression of SHMT2 and evaluate its prognostic value in patients with intrahepatic cholangiocarcinoma (iCCA)." (PMID 30228815, 2018).
thyroid cancer (7 papers, 2016 to 2025). "The functional importance of SHMT2 in thyroid cancers has led to the examination of metabolic pathways associated with the folate cycle in vitro." (PMID 38331894, 2024). "SHMT2 plays a distinct and pivotal role in thyroid cancer progression, particularly in ATC, where its expression is significantly upregulated compared with PTC and normal thyroid tissue." (PMID 40738465, 2025). "SHMT2 was expressed in all thyroid cancer cell lines, including normal thyroid (Nthy-ori 3-1), PTC (TPC-1 and BCPAP), and ATC (8505 C and FRO)." (PMID 38331894, 2024). "We examined the contribution of formate, an alternative carbon source, in the role of SHMT2 in thyroid cancer cell lines." (PMID 38331894, 2024). "In our experiments using thyroid cancer cells lines, knockdown or inhibition of SHMT2 showed similar effects in cell lines derived from PTC or ATC." (PMID 38331894, 2024). "Before observing the in vitro phenotype resulting from SHMT2 suppression, we examined the protein expression of SHMT2 in the original thyroid cancer cell lines." (PMID 38331894, 2024). "Next, we examined the effects of SHMT2 inhibition using SHIN2 on thyroid cancer cells." (PMID 38331894, 2024). "Next, to identify the role of SHMT2 while excluding off-target effects, we used the CRISPR/Cas9 system in thyroid cancer cell lines to confirm the effect of SHMT2 downregulation." (PMID 38331894, 2024). "Both the genetic knock-down of SHMT2 and treatment with an SHMT inhibitor inhibited the proliferation and migration of undifferentiated thyroid cancer cells and significantly reduced tumor growth in ATC in vivo." (PMID 38331894, 2024). "Since methylation of PTEN promoter has been reported in thyroid cancer and SHMT2 catalyzes the generation of methyl donor SAM, we hypothesized that SHMT2 represses PTEN expression via DNA methylation." (PMID 38272883, 2024). "However, the effects of SHMT2 inhibition on thyroid cancer cells have not yet been elucidated." (PMID 38331894, 2024).
glioblastoma (6 papers, 2016 to 2024). The most malignant astrocytic tumor (WHO grade IV). "SHMT2 was expressed in the pseudopalisading cells of human glioblastoma samples, and proliferation of the LN229 glioblastoma cell line was impaired or enhanced by SHMT2 suppression or overexpression under hypoxic conditions." (PMID 36175487, 2022). "In the SSP, SHMT2 and PSPH are upregulated but the upstream enzyme PSAT1 is downregulated in glioblastoma." (PMID 36175487, 2022). "SHMT2 and PSPH were upregulated and the upstream enzyme PSAT1 was downregulated, suggesting that SHMT2 and PSPH play key roles in activation of the SSP in glioblastoma." (PMID 36175487, 2022). "Our results showed that SHMT2 and PSPH were upregulated in SSP, while their upstream enzymes PSAT1 or PHGDH were downregulated or unaffected in glioblastoma, suggesting that the SSP in glioblastoma might be independent of carbon flux from glycolysis." (PMID 36175487, 2022). "In our study, both SHMT2 and PKM2 were upregulated in glioblastoma compared to near-normal brain." (PMID 36175487, 2022). "Moreover, SHMT2 and GLDC have been shown to antagonize the activity of PKM2 and reduce oxygen consumption in glioblastoma multiforme (GBM), thereby driving a survival advantage by reprogramming the metabolic state of the tumor." (PMID 39239102, 2024).
liver cancer (6 papers, 2016 to 2024). An epithelial or non-epithelial malignant neoplasm that arises from the liver. "For example, SHMT2 is highly expressed in liver cancer, and its knockdown can inhibit the progression of this disease." (PMID 38577602, 2024). "We started by investigating the therapeutic effect of inhibiting SHMT2 in liver cancer cell proliferation and tumorigenicity." (PMID 27391339, 2016). "In vitro, SHMT2-knockdown was found to reduce cell growth and tumorigenicity in Huh-7 and HepG2 liver cancer cells." (PMID 27391339, 2016). "Inhibition of SHMT2 led to reduced cell proliferation and tumorigenicity in liver cancer cells." (PMID 34476002, 2021). "However, overexpression of SHMT2 was insufficient to transform immortalized hepatic cells to malignancy, suggesting that SHMT2 is one of the building blocks in liver cancer metabolism but does not initiate malignant transformation." (PMID 27391339, 2016).
non-small cell lung carcinoma (6 papers, 2020 to 2023). A group of at least three distinct histological types of lung cancer, including non-small cell squamous cell carcinoma, adenocarcinoma, and large cell carcinoma. "In non-small-cell lung cancer (NSCLC), the transcriptional upregulation of SHMT2 by NRF2 supports the production of glutathione and nucleotides, which correlates with poor prognosis in NSCLC patients." (PMID 33456583, 2021). "Human non-small cell lung cancer with high NRF2 protein expression displayed significantly higher expression of ATF4, PHGDH, PSAT1, and SHMT2, which was significantly related to poorer prognosis and higher tumor grade." (PMID 32226297, 2020). "Our multi-omics analysis of aggressive, early-stage non-small cell lung cancer (NSCLC) revealed PHGDH, PSAT1 and especially SHMT2 as highly up-regulated compared to normal lung as a consequence of proteome remodelling, and showed PSPH gene amplification linked with EGFR." (PMID 32903271, 2020).
acute myeloid leukemia (5 papers, 2021 to 2025). Acute myeloid leukemia (AML) is a group of neoplasms arising from precursor cells committed to the myeloid cell-line differentiation. "NSUN2 also methylates mRNAs, where m5C stabilizes transcripts encoding key metabolic enzymes, including PHGDH and SHMT2, which are essential for serine/glycine biosynthesis and are implicated in acute myeloid leukemia (AML) progression and leukemic stem cell (LSC) self-renewal." (PMID 40973767, 2025). "In acute myeloid leukemia (AML), NSUN2 stabilizes PHGDH and SHMT2 mRNA and upregulates their expression by regulating m5C modification." (PMID 41462962, 2025).
lymph node metastasis (5 papers, 2021 to 2024). "Univariate analysis suggested that SHMT2 expression and lymph node metastasis were risk factors for overall survive of oral cancer patients." (PMID 33863325, 2021). "Overexpression of SHMT2 was associated with more advanced clinical and pathological characteristics such as advanced TNM stage and lymph node metastasis." (PMID 35211429, 2022). "Positive expression of SHMT2 was significantly correlated with TNM stage and lymph node metastasis, and elevated expression of SHMT2 resulted as an independent prognostic factor in patients with CRC." (PMID 35211429, 2022). "Similarly, high expression of SHMT2 and MTHFD2 was significantly associated with extrathyroidal extension (ETE), lymph node metastasis, stage III or IV, and the presence of the BRAFV600E mutation in the TCGA cohort." (PMID 38331894, 2024). "The result of multivariate analysis demonstrated that SHMT2, lymph node metastasis and differential degree could be independent prognostic factors affecting overall survive time of oral cancer patients." (PMID 33863325, 2021). "Male sex (p = 0.0026), aggressive histological grade (p = 0.0003), lymph node metastasis (p = 0.0012), distant metastasis (p = 0.0225), advanced AJCC stage (p = 0.0016) and lymphovascular invasion (p = 0.0012) were significantly associated with high SHMT2 expression." (PMID 36077112, 2022). "Significantly higher SHMT2 staining was also found in CRC with lymph node metastasis than in those without it (P=0.021)." (PMID 35211429, 2022).
osteosarcoma (5 papers, 2018 to 2025). A usually aggressive malignant bone-forming mesenchymal neoplasm, predominantly affecting adolescents and young adults. "Existing research has established that in osteosarcoma cell lines, succinylation at SHMT2-K280 causes the protein SHMT2 to form an inactive dimeric structure to suppress enzymatic function." (PMID 40865948, 2025). "Meanwhile, SHMT2 K280 succinylation is regulated by SIRT5, and the post-translational modification is inversely linked with osteosarcoma cell proliferation and tumor growth via regulation of the mitochondrion-carbon metabolism pathway." (PMID 40865948, 2025). "Similar experiments in human osteosarcoma U2OS cells also showed that NAM treatment enhanced SHMT2 acetylation." (PMID 30367038, 2018). "Therefore, succinylation of SHMT2 in osteosarcoma cells other than ESCC inhibits osteosarcoma cell growth by suppressing SHMT2 enzymatic activity and metabolic flow." (PMID 40865948, 2025). "Notably, Ewing sarcoma has a higher dependence on SHMT2 than osteosarcoma, a tumor for which antifolates represent the first-line therapy." (PMID 40698729, 2025).
B-cell lymphoma (4 papers, 2011 to 2024). "The SHMT2 gene is amplified in B cell lymphomas due to copy number gain, contributing to lymphoma development by epigenetic modulation of tumour suppressor gene expression." (PMID 38698089, 2024).